CDX1 (caudal type homeobox 1)
Description:
Plays a role in transcriptional regulation. Involved in activated KRAS-mediated transcriptional activation of PRKD1 in colorectal cancer (CRC) cells. Binds to the PRKD1 promoter in colorectal cancer (CRC) cells. Could play a role in the terminal differentiation of the intestine. Binds preferentially to methylated DNA.
Tractability: No criterion of Open Targets' tractability assessment is met for any kind of drug.
Gene: Protein-coding gene on chromosome 5 (150,166,778 to 150,184,558, forward strand). Ensembl gene ENSG00000113722.
Subcellular location: Nucleus
Gene Ontology:
Molecular function: DNA-binding transcription activator activity, RNA polymerase II-specific; methyl-CpG binding; protein binding; RNA polymerase II cis-regulatory region sequence-specific DNA binding; sequence-specific double-stranded DNA binding; transcription cis-regulatory region binding; DNA-binding transcription factor activity; DNA-binding transcription factor activity, RNA polymerase II-specific; RNA polymerase II transcription regulatory region sequence-specific DNA binding; DNA binding
Biological process: positive regulation of transcription by RNA polymerase II; animal organ morphogenesis; anterior/posterior axis specification; cell differentiation; digestive tract development; embryonic pattern specification; regulation of somitogenesis; regulation of transcription by RNA polymerase II; regulation of DNA-templated transcription
Cellular component: chromatin; nucleus
Genetic constraint (gnomAD): Loss-of-function variants: 9 observed, 9.45 expected, observed/expected ratio (o/e) 0.95, 90% interval 0.57 to 1.62. That is too few expected variants to judge how well the gene tolerates losing a copy. Missense variants: 393 observed, 283.9 expected, observed/expected ratio (o/e) 1.38, 90% interval 1.27 to 1.5. Synonymous variants: 179 observed, 132.01 expected, observed/expected ratio (o/e) 1.36, 90% interval 1.2 to 1.53.
Homologues: Orthologues: chimpanzee CDX1 (98% identical), macaque CDX1 (97% identical), dog CDX1 (89% identical), rabbit CDX1 (89% identical), rat Cdx1 (86% identical), mouse Cdx1 (85% identical), pig CDX1 (82% identical). Paralogues in human: CDX2 (50% identical), CDX4 (41% identical).
Diseases named in the same sentence as CDX1 in open-access papers:
CDX1 is named in the same sentence as 55 diseases in open-access papers, as found by Europe PMC text mining. Sharing a sentence is not in itself a finding about the gene and the disease. The quoted sentences say what the papers report.
colon carcinoma (16 papers, 2009 to 2025). "The loss of wt-Cdx1 and wt-Apc in colonic tumor organoids derived from cis-Apc+/−Cdx1+/− mice was confirmed by PCR." (PMID 40399276, 2025). "Organoids derived from colonic tumors carrying Cdx1 and Cdx2 mutations exhibited increased proliferation and elevated Lgr5 expression levels." (PMID 40399276, 2025). "Endoscopic analyses prior to endpoint revealed that loss of Cdx1 alone was sufficient to increase colon tumour formation, which was further increased in mice with compound Cdx1 and Ehf deletion." (PMID 35606410, 2022). "One target gene of HNF4A is galectin 4, which was described as tumor-suppressor in colon cancer, but also pancreatic duct adenocarcinoma, and was accordingly positively associated with high CDX1 mRNA expression in the current study." (PMID 30909444, 2019). "Although Cdx genes have mostly been implicated in regional identity, Cdx1 regulates cell adhesion through phosphorylation of catenins in human colon carcinoma cells." (PMID 24210613, 2013). "However, the role of CDX1/2 in regulating colon cancer stemness and the underlying mechanisms are unclear." (PMID 40399276, 2025). "We analyzed the gene expression profiles after expressing mouse wt-Cdx1 or wt-Cdx2 in human colon cancer-derived DLD1-TetOff cells." (PMID 40399276, 2025). "In this study, we analyzed the roles of CDX1/2 in the malignant progression of colon cancer, regulation of cancer stemness, and β-catenin-mediated transcription in colon cancer cells." (PMID 40399276, 2025). "CDX1/2 can inhibit colon cancer cell proliferation, and play roles in the stem cell function of normal intestinal epithelial cells and in colon cancer cell differentiation." (PMID 40399276, 2025). "In colonic tumor organoids derived from cis-Apc+/−Cdx1+/− and Cdx2+/−-cis-Apc+/−Cdx1+/− mice, the expression of Cdx1 and Cdx2 was lower than that in Apc+/− tumor organoids, whereas that of Lgr5 was higher." (PMID 40399276, 2025). "Triggered by our previous study, we here characterized the N-glycomic phenotype of 16 colon cancer cell lines, selected for their differential CDX1 mRNA expression levels." (PMID 30909444, 2019). "They found that the promoter region of the Caudal type homeobox 1 (CDX1) gene was methylated specifically in colon cancer cells." (PMID 28545228, 2017). "In the case of colon cancer, silenced TFs included well known intestinal differentiation factors such as CDX1, CDX2 and NEUROD1." (PMID 27562343, 2016). "We observed a similar trend of induction of pGL3/−1.2Cld-1-driven luciferase activity in HCT116 colon cancer, which was 2.5–3 fold upon overexpression of Cdx1 and GATA4 and ∼4-fold upon overexpression of Cdx2." (PMID 22719836, 2012). "The complete loss of Cdx1 resulted in extensive invasion of the small-intestinal tumor cells, whereas the absence of Cdx1 in conjugation with a heterozygous Cdx2 mutation led to the invasion of the colonic tumor cells." (PMID 40399276, 2025). "Similarly, the expression level of CDX1 in liver metastatic colon cancer tissues was lower than that in primary colon cancer tissues." (PMID 36224588, 2022). "Triggered by our previous findings, which suggested a relationship between increased multi-fucosylation (Lewis type glycan epitopes) and high CDX1 mRNA expression, here we characterized the N-glycosylation phenotype of a different set of colon cancer cell lines." (PMID 30909444, 2019). "The significance of the downregulation of CDX1, FABP1, and MAPT in CTCs is unknown, although associations between the losses of these genes and the development and progression of colon cancer have been described." (PMID 27340863, 2016).
colon carcinoma (continued). "Recent studies showed that CDX1 expression was down-regulated by promoter hypermethylation in colon cancer, whereas a subset of colon cancers may express increased levels of CDX1 mRNA and protein." (PMID 26683359, 2016). "However, there is no direct evidence of the regulation of colon cancer stemness and of expression of β-catenin-target genes by CDX1/2 (along with the underlying mechanisms)." (PMID 40399276, 2025). "It was reported that paclitaxel could induce autophagy only in Cdx1-expressing colon cancer cells, but not in Cdx1-deficient colon cancer cells." (PMID 24305604, 2013). "Among this group of genes, aberrantly methylated in other human cancers were CCR6 in oral cancer and chronic lymphocytic leukemia, RAB37 in lung cancer, ZNF521 in breast cancer, and CDX1 in gastric cancer, esophageal SCC, and in colon cancer." (PMID 32961999, 2020). "In contrast, a direct involvement of CDX2 in the regulation of FUT2, which revealed potential binding sites for CDX1 and CDX2 and is involved in the generation of LeY/B antigens, was shown in colon cancer cell lines HT29 and DLD-1." (PMID 30909444, 2019). "Taken together, we conclude that homeodomain transcription factors Cdx1, Cdx2 and GATA4 regulate claudin-1 gene expression in human colon cancer cells." (PMID 22719836, 2012). "Our further studies using full length and/or deletion mutant constructs in two different human colon cancer cell lines, SW480 and HCT116, showed key role of Cdx1, Cdx2 and GATA4 in the regulation of claudin-1 mRNA expression." (PMID 22719836, 2012). "To directly assess the impact of CDX1 and CDX2 on MS4A12 transcript and protein expression we silenced both factors in LoVo and SW48 colon cancer cells by transient transfection with specific siRNA duplexes." (PMID 19781065, 2009). "However, CDX1/2 and β-catenin–TCF4 complex exhibit antagonistic functions, potentially inhibiting each other within the shared genome of colon cancer cells." (PMID 40399276, 2025). "Next, we depleted CDX1 and KLF4 in SW1222 colon cancer cells by siRNA." (PMID 39472498, 2025). "RNA interference (RNAi)-mediated silencing of intestine-specific transcription factors CDX1 and CDX2 and chromatin immunoprecipitation (ChIP) in LoVo and SW48 colon cancer cells revealed that MS4A12 transcript and protein expression is essentially dependent on the presence of endogenous CDX2." (PMID 19781065, 2009).
gastric cancer (14 papers, 2007 to 2023). A primary or metastatic malignant neoplasm involving the stomach. "Overexpression of miRNA-9 and miRNA-326 is correlated with gastric cancer carcinogenesis, which targets caudal type homeobox 1 (CDX1) and CDX2 (tumor suppressors) by promoting hypermethylation of the promoter region of CDX1 and CDX2." (PMID 36765652, 2023). "Recently, single patient classifier (SPC) genes, such as secreted frizzled-related protein 4 (SFRP4) and caudal-type homeobox 1 (CDX1), were associated with prognosis and chemotherapy response in stage II–III gastric cancer." (PMID 35683460, 2022). "Other targets of MIR296 are the proto-oncogenes AKT2 in pancreatic cancer, PLK1 in non-small cell lung cancer, SP1 in cervical cancer and CDX1 in gastric cancer." (PMID 32582296, 2020). "CDX1 promoter methylation was highly consistent with NF-κB signal activation, but inversely associated with TNF-α expression in the carcinogen-induced stomach cancer development." (PMID 29467412, 2018). "For example, the over-expression of miR-296-5p significantly promoted gastric cancer cell proliferation and attenuated CDX1-induced anti-growth effects by regulating cell cycle distribution and apoptotic status." (PMID 28178677, 2017). "The expression of miR-296-5p is abnormally increased in gastric cancer, which inhibits the expression of caudal-related homeobox 1 (CDX1)." (PMID 27464701, 2016). "Cdx2 was bound to the Cdx1 promoter region in the intestinal metaplasia and the normal intestine, and upregulated the transcriptional activity of the Cdx1 gene in the human gastric carcinoma." (PMID 23181722, 2012). "The association of Sox2 and Cdx2 genes has also been shown in a different system, that of gastric cancer where Sox2 and Cdx1/Cdx2 are inversely related." (PMID 21103067, 2010). "Staining was used to detect Cdx1, Cdx2, Muc2 and Muc5AC and it was revealed that Cdx1 and Cdx2 were consistently expressed in IM and in a subset of gastric carcinomas." (PMID 19412438, 2007). "Furthermore, gland structure in antral tumors, together with the ectopic expression of CDX1, CDX2 and Villin, the well-known intestinal epithelial markers, suggested that gastric cancer caused by Prmt5 deletion was intestinal-type gastric cancer." (PMID 35864961, 2022). "Moreover, CDX1 was found to be a predictive marker for chemotherapy response in stage II–III gastric cancer from the previous study." (PMID 35683460, 2022). "They reported that Cdx1 and Cdx2 expression was independent of the type of IM and of gastric carcinoma, and that it was significantly associated with expression of the intestinal mucin Muc2." (PMID 19412438, 2007). "It is shown that Signal Transducer and Activator of Transcription 3 (STAT3) and caudal type homeobox 1 (CDX1) promote SALL4 expression in breast and gastric cancers, respectively." (PMID 36010677, 2022). "Treating gastric cancer cell lines (AGS and MKN4) with SFN led to the decreased proliferation, apoptosis induction, and reduced expression of miRNA-9 and miRNA-326, and thereby, SFN enhanced levels of CDX1 and CDX2 in AGS and MKN4." (PMID 36765652, 2023). "Specifically, CDX1 has been reported to play vital roles in gastric intestinal metaplasia, and the identified miR-296-5p-CDX1-ERK1/2 axis elucidates our the understanding of the progression from intestinal metaplasia to gastric cancer." (PMID 28178677, 2017). "In addition to tumor suppressors, we also observed several candidate oncogenes to be expressed at lower levels in EBVaGCs including 4 (CDH17, CDX1, ETV4, and PPP1R1B) known to be over expressed in gastric carcinoma and gastrointestinal cancers." (PMID 23671415, 2013).
colorectal cancer (11 papers, 2009 to 2024). A primary or metastatic malignant neoplasm that affects the colon or rectum. "The Cdx transcription factors Cdx1 and Cdx2 are essential for homeostasis of the intestinal epithelium, and loss of Cdx2 has been associated with more aggressive subtypes of colorectal cancer in the human population." (PMID 33525395, 2021). "By screening different colorectal cancer cell lines, we previously showed an association of caudal-related homeobox protein 1 (CDX1) mRNA expression with increased multi-fucosylation (more than one fucose), which is indicative for antenna fucosylation." (PMID 30909444, 2019). "Altogether, our data highlight a possible role of CDX1 in altering the N-glycosylation of colorectal cancer cells, which is a hallmark of tumor development." (PMID 30909444, 2019). "For example, CDX1 (an AP-2α target) is highly expressed in colorectal carcinoma (COAD and READ cohorts) but it is also expressed to a certain extent in STAD." (PMID 35361846, 2022). "The transcription factor Cdx2, and to a lesser extent Cdx1, plays essential roles in intestinal homeostasis, and acts as a context-dependent tumour suppressor in colorectal cancer." (PMID 34349205, 2021). "Wong et.al showed that the methylation of CDX1 induced the low level of CDX1 expression in some colorectal cancer cell lines." (PMID 31262330, 2019). "Taken together, these results indicate that CEACAM6 is involved in an acid- or hypoxia-triggered stress response in colorectal cancer cells but is not linked to HIF1α signaling or under control by CDX1/2." (PMID 38502695, 2024). "To validate our previous results and to further explore expression profiles of associated fucosyltransfereases, we characterized the N-glycosylation of an independent set of colorectal cancer cell lines with high (8 cell lines; CDX1high) vs. low (8 cell lines; CDX1low) expression of CDX1 mRNA." (PMID 30909444, 2019). "A number of genes are commonly hypermethylated in colorectal cancer (CRC) including hMLH1, p16INK4a, p14ARF, RAR-β, APC, MGMT, cyclin A1, CDX1, MYOD1, COX-2 and WT-1." (PMID 19662090, 2009). "Our previous data suggested a positive association between the level of fucosylation on protein N-glycans and CDX1 mRNA expression in a set of colorectal cancer cell lines (15 cell lines CDX1/villin positive, 7 cell lines CDX1/villin low or negative)." (PMID 30909444, 2019).
Barrett esophagus (4 papers, 2008 to 2024). Esophageal lesion lined with columnar metaplastic epithelium which is flat or villiform. "Analyses of these cultures reveal that c-myc and cdx1 cooperate to induce mucin production and changes in keratin expression that are observed in the epithelium of Barrett's esophagus." (PMID 18953412, 2008). "Cdx1 expression decreases in adenomatous polyps and correlates with increased dysplasia in Barrett's esophagus." (PMID 18953412, 2008). "The CDX1 and CDX2 expression promotes the transdifferentiation of the normal squamous epithelium into the columnar epithelium with intestine-like features, which is a significant risk factor for the development of esophageal adenocarcinoma." (PMID 38473997, 2024). "Through a microarray comparison of the normal stratified squamous epithelium of the esophagus, Barrett's esophagus and the normal small intestine, and accompanying validation, the molecular signature of Barrett's esophagus highlights the importance of both Cdx1 and c-myc." (PMID 18953412, 2008). "Taken together, these data suggest that c-myc and Cdx1 transcription factors may contribute to in the transdifferentiation process leading to Barrett's Esophagus." (PMID 18953412, 2008). "This, in combination with the fact that c-myc is already expressed in esophageal keratinocytes, suggest that c-myc and Cdx1 may cooperate in some of the very earliest initiation stages towards Barrett's Esophagus." (PMID 18953412, 2008). "Interestingly, a similar type of Cdx1 regulation has been observed in Barrett's esophagus and intestinal-type gastric adenocarcinoma." (PMID 18953412, 2008). "We believe that c-myc and Cdx1 cooperate to induce the initiation of a normal stratified squamous epithelium towards a transdifferentiated state and that Barrett's esophagus requires additional genetic events for the development of a fully mature transdifferentiation process." (PMID 18953412, 2008). "For example, cytokine release, triggered by reflux-related inflammation, can lead to the expression of CDX1 and CDX2, intestine-specific factors, in Barrett’s esophagus." (PMID 38473997, 2024). "Likewise, Cdx1 may be functionally related to the development of Barrett's esophagus." (PMID 18953412, 2008). "In order to model Barrett's Esophagus, EPC2-hTERT Myc cells alone or with Cdx1 were cultured in a 3-dimentional culture system (organotypic culture) previously utilized in our lab to mimic the microenvironment of the esophagus to study esophageal tumorigenesis." (PMID 18953412, 2008).
glioma (4 papers, 2017 to 2025). A benign or malignant brain and spinal cord tumor that arises from glial cells (astrocytes, oligodendrocytes, ependymal cells). "For example, miR-24, which is highly expressed in gliomas, accelerated glioma cell growth by targeting caudal-type homeobox 1 and activating the PI3K/Akt pathway." (PMID 38267974, 2024). "miR-24 promotes glioma development by acting on the caudal-type homeobox 1 (CDX1) target to activate the PI3K/Akt signaling pathway, promote cell proliferation, and induce apoptosis." (PMID 36479040, 2022). "Further analysis revealed that miR-155 negatively correlates with caudal-type homeobox 1 protein (CDX1) expression in glioma tissues and promotes the progression of tumor formation and poor overall survival." (PMID 29280958, 2017).
breast carcinoma (3 papers, 2012 to 2021). "The authors also found that XIST sponged miR-155, which in turn upregulated the expression of caudal-type homeobox 1 (CDX1) and inhibited the progression of breast cancer." (PMID 34527584, 2021). "We further confirmed specificity of our findings to the colonic claudin-1 expression as similar transient overexpression of Cdx1, Cdx2 or GATA4 in human breast cancer cells (MCF-7) or renal epithelial cells (MDCK II cells) did not increase claudin-1 promoter activity." (PMID 22719836, 2012). "Further, our finding that similar overexpression of Cdx1, Cdx2 or GATA4 in the renal epithelial and breast cancer cells had no apparent effect upon claudin-1 expression suggest that this is not a universal mechanism of claudin-1 expression and is rather colon specific." (PMID 22719836, 2012).
cervical cancer (3 papers, 2020 to 2024). A primary or metastatic malignant neoplasm involving the cervix. "For example, FOXD2-AS1 is upregulated in cervical cancer tissues especially in samples with advanced tumor staging, and it promotes cervical cancer malignant progression by decreasing CDX1 level." (PMID 38807101, 2024). "FOXD2-AS1 depletion can also regulate the expression of CDX1 and inhibit the proliferation of cervical cancer cells." (PMID 34872450, 2021).